INS (insulin)
Diseases named in the same sentence as INS in open-access papers (continued):
Sharing a sentence is not in itself a finding about the gene and the disease.
Obesity (continued). "Together, ATMs respond to their environment by upregulating lipid/lysosomal programs, which is likely heighted during obesity, allowing them to fulfill their main function of clearing up dying adipocytes, buffering lipids, preventing ectopic lipid spill over, and ensuing insulin resistance." (PMID 31497027, 2019). "However, the opposite effect was reported to occur when IL4 was administered intracerebroventricularly (icv) to rats during HFD feeding, that is, exacerbation of obesity, further hypothalamic inflammation as well as leptin and insulin resistance." (PMID 30158466, 2018). "Indeed, resistance to anorexigenic signaling pathways are well-characterized in obesity (e.g., leptin and insulin), including neuropeptides such as CARTPT." (PMID 29746501, 2018). "However, the precise mechanisms via which these cells impair insulin sensitivity require further investigation, especially in human obesity." (PMID 29549282, 2018). "In general, sleep loss and decreased sleep quality without the presence of OSA is associated with obesity, impairments in glucose regulation, and reductions in insulin sensitivity." (PMID 30127766, 2018). "Atg-7 knockout mice are insulin-sensitive and resistant to the development of obesity." (PMID 29507613, 2018). "RBP4 is a 21 kDa secreted protein elevated in insulin resistant states such as obesity and T2DM." (PMID 30186876, 2018). "At the same time, Epi-fat weight increase with a reciprocal reduction in liver weight was observed in Postn−/− mice, which indicated that the adipose tissue fibrosis induced by Postn is a detrimental factor for ectopic lipid disposition and insulin resistance in obesity." (PMID 29867212, 2018). "In addition boys with obesity had higher concentrations of insulin and leptin and lower concentrations of HDL-cholesterol compared to normal weight boys." (PMID 30266914, 2018). "Emerging hypotheses postulate that physiological components of obesity, including glycemic control, insulin action, and leptin signaling, contribute to the development of OSA." (PMID 30127766, 2018). "Correlations of obesity measures to various insulin and glucose ratios (R2, P-values by ANOVA)." (PMID 30001422, 2018). "Specifically, we tested the hypothesis that EVs released by stressed adipocytes and those found circulating in human obesity impact on insulin‐stimulated glucose uptake." (PMID 29292863, 2018). "Additionally, correlation analysis demonstrated that plasma asprosin levels were significantly correlated with parameters regarding glucose metabolism, obesity, lipid profiles, insulin resistance, and β-cell function." (PMID 29743813, 2018). "Similarly, a more recent study reported that women with overweight and obesity displayed a greater reduction in insulin and a greater elevation in acylated ghrelin than men in the postprandial state, after a short four-day exercise program." (PMID 30131457, 2018). "Similarly, for the obesity study there is a high correlation between c-peptide of insulin and insulin; total bilirubin and albumin; and hemoglobin, serum creatinine and uric acid." (PMID 29650030, 2018). "At the baseline, the subjects with obesity had significantly higher body weight, BMI, WC, soft lean mass, visceral fat mass, waist to hip ratio, fasting glucose, insulin, HOMA-IR, triglycerides, uric acid, WBC, hs-CRP, ALT, γ-GT, C-peptide, and NFS than those in the normal BMI group." (PMID 30458048, 2018). "The old view that higher insulin response leads to obesity is gaining grounds once again." (PMID 30151194, 2018). "A study on how obesity might promote carcinogenesis suggested that obesity elevates insulin production, which might drive tumor growth." (PMID 29343838, 2018). "The restoration in insulin sensitivity, probably secondary to reduced ceramide levels, emphasize one of the most important benefits of LSG in reducing comorbidities associated with obesity." (PMID 30474555, 2018).
Obesity (continued). "In the stage of obesity with retained insulin sensitivity, M2-polarized resident adipose tissue macrophages (ATMs) are able to partially protect adipocytes from these inflammatory factors and may block M1 polarization." (PMID 29348470, 2018). "SST may also act on obesity by limiting insulin release, which is the primary hormonal mediator of adipogenesis in humans." (PMID 30053852, 2018). "Thus, fully comprehending the mechanism of insulin signaling pathways and other biological processes in the adipose tissue is beneficial for exploring a potential target of obesity treatment." (PMID 29522441, 2018). "We also considered whether circulating Ly6Chigh monocytes can be modulated by glucose and insulin in the context of diet‐induced obesity." (PMID 30548217, 2018). "In addition, IL-15 is directly related to muscle metabolism, or even diet-induced obesity and insulin sensitivity." (PMID 30319436, 2018). "Furthermore, in a mouse model, metformin inhibited lung cancer cell growth induced by hyperinsulinemia and obesity by decreasing the circulating level of insulin and by activating the AMPK pathway." (PMID 30186236, 2018). "Our data indicate that reduction in AT inflammation is not required for an improvement in insulin action during weight loss in subjects with uncomplicated obesity." (PMID 29737494, 2018). "Interestingly, GPR6 knockout mice exhibit hyperphagia-induced obesity and higher liver triglyceride content, plasma insulin, and leptin levels compared to wild-type mice." (PMID 30564199, 2018). "Our data suggest that subjects who gained weight may be more insulin resistant than those who maintained the same degree of obesity." (PMID 29487293, 2018). "Furthermore, the development of beiging adipocytes within WAT has potential anti-obesity and insulin-sensitizing effects." (PMID 29391544, 2018). "Thus, the result of pharmacological intervention in obesity with TZDs is the improvement of insulin sensitivity derived from the effects of TZDs improving adipose tissue function despite the associated increase in fat mass." (PMID 30037087, 2018). "The apparently contradictory effects of obesity-associated downregulation of Atg7 and genetic knockout of Atg7 on hepatocyte insulin resistance may be better understood by considering that Atg7 knockout prevents obesity." (PMID 30116482, 2018). "Furthermore, plasma ghrelin levels have been reported to be reduced in animal models of obesity and in obese subjects, being inversely correlated with adiposity, fasting insulin, and leptin." (PMID 29618984, 2018). "Likewise, individuals with overweight or obesity display elevated concentrations of leptin and insulin." (PMID 30131457, 2018). "Furthermore, in a randomized controlled trial comparing resistance versus aerobic exercise in adolescent boys with obesity, improvements in insulin sensitivity were observed with resistance exercise alone." (PMID 29471797, 2018). "In this study, we investigated the effects of beef protein, casein, and soy protein in both lean and obese C57BL6/J mice [which were fed high-fat diet (HFD) to induce obesity] by examining lipid metabolism, triglyceride accumulation, insulin resistance, and colonic microbial diversity." (PMID 30319558, 2018). "Impaired insulin sensitivity, which may appear prior to glucose dysregulation in adolescents, is a major component of obesity and its co-morbid diseases, such as T2DM and cardiovascular disease (CVD)." (PMID 29471797, 2018). "In addition, obesity is correlated with T2D through proinflammatory cytokines (adipokines), insulin sensitivity, abnormal fatty acid metabolism, and intracellular disturbances; mitochondrial dysfunction and endoplasmic reticulum stress." (PMID 30557342, 2018). "Thus, these adaptive changes in synaptic strength appear to be a hallmark feature of negative energy balance (in the case of fasting) as well dysregulated energy balance (in the case of obesity and insulin/leptin resistance)." (PMID 29973869, 2018).
Obesity (continued). "Continuous cerebral administration of FGF-21 for 2 weeks increased whole body insulin sensitivity in rats with dietary-induced obesity, whilst daily intravenous or subcutaneous delivery of FGF-21 for 6 weeks improved glucose handling in diabetic rhesus monkeys." (PMID 29760587, 2018). "In the present study, we investigated brain insulin signaling and tau expression in experimental animals that exhibited obesity induced by a long-term HFD, rather than by genetic mutations or drug treatments." (PMID 29673239, 2018). "As expected, the highest basal insulin was found in the obesity group." (PMID 30131769, 2018). "However, leptin's tight relationship with other key players in OSA, including obesity and insulin sensitivity, especially in T2D individuals, make it difficult to draw specific conclusions about the role of leptin in OSA." (PMID 30127766, 2018). "Furthermore, decreased insulin sensitivity is a critical factor which accelerates independent risk factors of CVD including hypertension, obesity, and dyslipidemia." (PMID 30276217, 2018). "However, contradictory findings suggest that XBP-1, which has glucose-lowering and insulin-sensitizing effect in obesity, induces, in concert with NF-κB, the transcription of genes encoding inflammatory cytokines such as interleukin 1β." (PMID 29847581, 2018). "As it has been well accepted that improvement of insulin sensitivity always occurs after reduction of obesity, it can be argued that the observed beneficial metabolic effects upon leucine deficiency in most other studies is likely a result of body weight reduction." (PMID 30294696, 2018). "Besides that, obesity induced by hormonal imbalances is connected to a range of adverse health complications as a result of cardiovascular abnormalities and insulin resistance." (PMID 30400600, 2018). "In addition, it has also been demonstrated that insulin’s ability to stimulate glucose oxidation is severely diminished in the hearts of animals or humans with obesity and/or T2D." (PMID 29560354, 2018). "Interestingly, the only HIIT combined with RT study to report BP change also included only male participants with moderate-duration T2D with similar HbA1c as our participants (but with lower levels of baseline obesity and all using exogenous insulin)." (PMID 30210450, 2018). "Butyrate can improve HFD-induced obesity and insulin sensitivity." (PMID 30135362, 2018). "The degree of obesity may also be an important determinant of subcutaneous insulin kinetics, and results obtained in overweight or moderately obese subjects may not be translated to those more severely obese." (PMID 30114246, 2018). "Furthermore, obesity was associated with elevated plasma TAG, cholesterol, CRP and serum insulin concentrations, and increased HOMA‐IR (P < 0.05)." (PMID 30009507, 2018). "However, TNFα and IL-6 not only impact systemic insulin sensitivity in obesity, but also promote cancer, since these cytokines are also produced from cells of the tumor microenvironment." (PMID 30591653, 2018). "Moreover, the expression of the insulin-sensitizing adipokine—adiponectin is strikingly down-regulated in obesity." (PMID 29507613, 2018). "In the state of obesity, excessive energy triggers NF-κB signaling pathways and may disrupt insulin signaling pathway via induction of TNF-α secretion by WAT, which in turn causes IR37." (PMID 29487289, 2018). "In conclusion, our results suggest that mangosteen could potentially represent an appealing treatment of obesity and its comorbidities, most importantly insulin resistance, given its favorable cost/benefit ratio." (PMID 29747432, 2018). "This study investigated the effects of 8 weeks of HIIT on blood and skeletal muscle markers related to IR and oxidative metabolism in physically inactive individuals with obesity and compared the changes between insulin resistant and non-insulin resistant phenotypes." (PMID 30429793, 2018).
Obesity (continued). "However, studies evaluating the impact of exercise on insulin sensitivity in children and adolescents with obesity have been inconsistent." (PMID 29471797, 2018). "Obesity is related with augmented insulin levels, which may lead to elevated insulin-like growth factor 1 and synthesis of androgens that ultimately cause progesterone deficiency." (PMID 30400600, 2018). "A second study of Canadian youth at risk of obesity reported an association of added sugars from liquid sources but not solid sources with higher fasting glucose and insulin levels." (PMID 28711418, 2018). "In mice, deletion or functional inactivation of CEACAM1 impairs insulin clearance and compromises metabolic homeostasis which initiates the development of obesity and hepatic steatosis and fibrosis with other features of non-alcoholic steatohepatitis, and adipogenesis in white adipose depot." (PMID 30314283, 2018). "In contrast to our findings, however, many of these studies show that obesity-associated dysregulation of insulin and glucose signaling was improved in the absence of TLR4 signaling." (PMID 30396359, 2018). "Changes seen in these two key hormonal systems in obese subjects allow us to predict the impact of obesity on the main metabolic organs as a consequence of modified insulin sensitivity for example, especially with the interactions between leptin and insulin and the distribution of leptin receptors." (PMID 30463389, 2018). "Moreover, fat-specific FASN knockout mice were protected from high-fat diet-induced obesity and exhibited an improvement of glucose tolerance and insulin sensitivity." (PMID 30274245, 2018). "The positive effect of coconut oil supplementation on the glycemic profile in the present study is consistent with the findings from studies in rats, which reported an improvement in glycemia and insulin response in individuals with obesity when supplemented with MCFAs." (PMID 30037019, 2018). "Therefore, the advised inhibition of DPP-IV activity is considered to evoke multiple sets of physiological responses to resist T2DM and obesity via facilitating tyrosine phosphorylation of insulin signalling molecules." (PMID 35541310, 2018). "The rationale was that suppression of autophagy by insulin may contribute to decreased protein degradation with obesity as a result of chronic hyperinsulinemia." (PMID 30047243, 2018). "Elevated insulin concentrations have been observed in individuals with T2D following consumption of a large breakfast, but not in response to a chronic large breakfast meal pattern in women with overweight or obesity." (PMID 29882811, 2018). "This is particularly important as ghrelin and insulin-induced increases of PI3K and MAPK may be linked to an energy-rich state such as obesity, as these pathways regulate cell proliferation." (PMID 29462993, 2018). "In aging, as in obesity, mitochondrial enzyme expression is reduced in the AT leading to decreased oxygen consumption and oxidative phosphorylation in response to lipid overload, usually coupled with decreased AT insulin sensitivity." (PMID 30037087, 2018). "According to the “carbohydrate-insulin theory of obesity” fasting periods in-between meals are important, because the decrease in insulin levels activates lipolysis and lipid oxidation which may improve fat balance." (PMID 29695707, 2018). "In addition, this study assessed parameters possibly influencing cognitive functions, that is, insulin sensitivity, inflammation, glycemic control, and overweight/obesity." (PMID 30159333, 2018). "We have also demonstrated that the antiangiogenic factor secreted frizzled-related protein 4 (SFRP4) is associated with adipose tissue rarefaction (capillary drop out) and may lead to inflammation and ultimately insulin resistance in people with obesity." (PMID 29721017, 2018).
Obesity (continued). "Adjusting for mean insulin dose per maternal body weight (kg) over gestation, total GWG per kg was associated with non-statistically significant increased odds (aOR = 1.51, [95%CI: 0.96–2.39], p = 0.07) for overweight/obesity among offspring at follow-up." (PMID 30559715, 2018). "This experimental study revealed that the levels of hypothalamic leptin and insulin in the cerebral blood of the obesity rats were significantly lower than those in the cerebral blood of the normal rats, whereas the result of those levels in the peripheral blood was opposite." (PMID 29853949, 2018). "In addition, it has been confirmed that the long-term rhGH treatment can improve the insulin sensitivity in adult obesity by normalizing lipid metabolism and body composition." (PMID 29615058, 2018). "Physical activity has been shown to increase insulin sensitivity, while obesity decreases insulin sensitivity and it is possible that the interaction of the two can result in more benefit from increased physical activity for high BMI subgroups with respect to CRC risk reduction." (PMID 29325535, 2018). "In addition to the findings of these immune-regulatory genes, many other top associations have been implicated in obesity (AEBP2) (FDR < 0.10), calcium signaling (CAPNS1), insulin signaling (INSR, PTPRN2, RPTOR), and vasodilation (VASP)." (PMID 29692868, 2018). "Similarly in obesity study, insulin has high significance in males and HBA1C% has high significance in females." (PMID 29650030, 2018). "Alternatively, it has been hypothesized that insulin resistance and subsequent hyperinsulinemia induced by obesity may lead to direct mitogenic and antiapoptotic signaling by insulin or insulin-like growth factor axis." (PMID 29288474, 2018). "In addition, a plethora of published evidence demonstrates that TNF-α directly affects insulin signaling in high-fat-diet-induced obesity." (PMID 29408929, 2018). "We compared sex hormones between healthy and PCOS females and the metabolic profiles between subgroups of PCOS patients, finding that overweight/obesity, excess insulin and androgen secretion, and reduced estradiol and progesterone all had a higher prevalence in PCOS females." (PMID 30524197, 2018). "Genetic depletion of Ahnak protects from obesity and enhances insulin sensitivity." (PMID 30154465, 2018). "Moreover, PTP1B knockout mice are highly sensitive to insulin, have low adiposity, and are protected from diet-induced obesity." (PMID 29373583, 2018). "Accordingly, because DM2 is preceded by a period of IR, the measurement of both fasting insulin and glucose in children and adolescents with obesity is recommended, particularly in subjects who had the presence of acanthosis nigricans and a family history of DM2." (PMID 30254673, 2018). "Furthermore, previous studies have also highlighted the beneficial effects of lifestyle interventions on insulin secretion and β-cell function in adults with obesity." (PMID 29471797, 2018). "In conclusion, our data indicate that reduction in AT inflammation is not required for an improvement in insulin action during weight loss in subjects with uncomplicated obesity." (PMID 29737494, 2018). "Whereas knockout of Il-1r1 gene causes leptin resistance and obesity, Ptpn1 knockout results in negative energy balance, protection from weight gain and improved insulin sensitivity." (PMID 29371411, 2018). "Following the same line of thought, and due to the strong hormonal component in obesity, hormonal pathways (such as leptin and insulin-related) still deserve further investigations to identify novel molecular targets within the obesity-related pathways of these hormones." (PMID 30463389, 2018). "Moreover, a recent meta-analysis that included nine randomized controlled trials reported improvements in insulin resistance markers in youth with obesity with aerobic exercise programs lasting > 12 weeks." (PMID 29471797, 2018).